REXO1 (RNA exonuclease 1 homolog)
Description:
Seems to have no detectable effect on transcription elongation in vitro.
Synonyms: EloA-BP1; ELOABP1; KIAA1138; TCEB3BP1; REX1
Tractability: PROTAC: ubiquitination databases record sites on it.
Gene: Protein-coding gene on chromosome 19 (1,815,248 to 1,848,493, reverse strand). Ensembl gene ENSG00000079313.
Subcellular location: Nucleus
Subcellular location (Human Protein Atlas): Nucleoplasm; Nuclear bodies
Gene Ontology:
Molecular function: exonuclease activity; nucleic acid binding
Biological process: rRNA 3'-end processing
Cellular component: nuclear body; nucleoplasm; nucleus
Genetic constraint (gnomAD): Loss-of-function variants: 40 observed, 84.59 expected, observed/expected ratio (o/e) 0.47, 90% interval 0.37 to 0.62. The synonymous counts are far from expectation, so gnomAD's model fits this gene poorly and the ratio says little. Missense variants: 1,753 observed, 1,550.9 expected, observed/expected ratio (o/e) 1.13, 90% interval 1.09 to 1.18. Synonymous variants: 874 observed, 686.46 expected, observed/expected ratio (o/e) 1.27, 90% interval 1.2 to 1.35.
Homologues: Orthologues: macaque REXO1 (96% identical), chimpanzee REXO1 (95% identical), pig REXO1 (81% identical), dog REXO1 (80% identical), guinea pig REXO1 (79% identical), mouse Rexo1 (78% identical), rat Rexo1 (76% identical), tropical clawed frog rexo1 (46% identical). Paralogues in human: REXO5 (8% identical), REXO4 (8% identical), ISG20L2 (6% identical), AEN (6% identical), ISG20 (4% identical).
Diseases named in the same sentence as REXO1 in open-access papers:
REXO1 is named in the same sentence as 4 diseases in open-access papers, as found by Europe PMC text mining. Sharing a sentence is not in itself a finding about the gene and the disease. The quoted sentences say what the papers report.
cervical cancer (3 papers, 2021 to 2025). A primary or metastatic malignant neoplasm involving the cervix. "Little is known about the protein encoded by the REXO1 gene, other than its participation in RNA polymerase II transcription via Elongin A and its role promoting cervical cancer cell proliferation and progression." (PMID 35033200, 2022). "In cervical cancer, circ-CCDC66, a molecular sponge of miR-452-5p, can upregulate REXO1 expression by blocking the action of miR-452-5p to promote cell proliferation, migration, invasion, and accelerate cervical cancer progression." (PMID 40181128, 2025). "Subsequently, we investigated the role of circ-CCDC66/miR-452-5p/REXO1 axis in cervical cancer cellular progression." (PMID 33407514, 2021). "It was found that circ-CCDC66 was an efficient molecular sponge for miR-452-5p, and miR-452-5p directly targeted to REXO1 in cervical cancer cells." (PMID 33407514, 2021). "Subsequently, our study found that miR-452-5p directly targeted to REXO1, and negatively regulated REXO1 expression in cervical cancer cells." (PMID 33407514, 2021). "One the other hand, the downstream molecular mechanisms of REXO1 in cervical cancer progression need further exploration." (PMID 33407514, 2021). "Collectively, our study demonstrated the role of circ-CCDC66/miR-452-5p/REXO1 pathway in cervical cancer progression." (PMID 33407514, 2021). "The biological effects of REXO1 on cervical cancer cells were evaluated." (PMID 33407514, 2021). "Our results demonstrated the role of circ-CCDC66/miR-452-5p/REXO1 axis in cervical cancer progression, we might provide novel therapeutic targets for cervical cancer clinical intervention." (PMID 33407514, 2021). "Circ-CCDC66 regulated REXO1 expression to modulate cervical cancer progression via miR-452-5p." (PMID 33407514, 2021). "CCK-8 and Transwell assays showed that the inhibitory effects of downregulated circ-CCDC66 on Hela and SiHa cells were rescued by REXO1 overexpression, suggested that circ-CCDC66 regulated REXO1 expression to promote cervical cancer progression via sponging miR-452-3p." (PMID 33407514, 2021). "Moreover, our results demonstrated that circ-CCDC66 promoted cervical cancer progression via miR-452-5p/REXO1 axis, indicating that circ-CCDC66 might be a novel therapeutic target for cervical cancer." (PMID 33407514, 2021).
breast carcinoma (1 paper, 2023). "Increased DNA methylation in genomic regions associated with SURF6 and REXO1/CTB31O20.3 was linked to the length of time to diagnosis in the prospectively collected buffy coat DNA from individuals who subsequently developed breast cancer." (PMID 37309009, 2023).
viral infection (1 paper, 2019). "Our data further identified numerous ribonuclease and deoxyribonuclease genes with unknown roles in viral infection such as Dnase1l3, Dclre1c, Rexo1, Dxo, and Mgme1." (PMID 31057555, 2019).
REXO1 also shares sentences with these, for which no sentence is quoted: cancer (1 paper).